CD274 (CD274 molecule)
Diseases named in the same sentence as CD274 in open-access papers (continued):
Sharing a sentence is not in itself a finding about the gene and the disease.
cancer (continued). "Finally, the immune checkpoint receptor PD-1 is also expressed by NK-cells, resulting in a robust inhibitory signal upon binding to its ligand CD274 (PD-L1), frequently overexpressed on cancer cells." (PMID 33265951, 2020). "Interestingly, we did not see an increase in expression among genes that are associated with immunosuppression in cancer (such as ARG1, CD274, COX2, PGE2, and NOS2)." (PMID 33659259, 2020). "Our results demonstrated that synergism blockade CD47 and CD274 antibody in cancer can also inhibit tumor growth and CTCs metastasis in vivo, which may block CD47 binding to SIPR-α and PD-L1 binding to PD-1." (PMID 30872703, 2019). "To evaluate whether synergy blocking of CD47 and CD274 on cancer cells could be effectively against CTCs in the lungs, we employed a well-established CTCs 4T1 model, which spontaneously developed lung metastasis." (PMID 30872703, 2019). "It has been confirmed that combination CD47 and CD274 is an excellent method for cancer therapy." (PMID 30872703, 2019). "First, we determined expression of CD47 and CD274 in mouse cancer cells." (PMID 30872703, 2019). "We confirmed THE expression of CD47 and CD274 in a series of mouse cancer cells." (PMID 30872703, 2019). "Five additional proteins were studied: carcinoma stem cell markers: TRA-1-60, CD326 (epithelial cell adhesion molecule, EpCAM), galectin-3 (GAL-3), the immune checkpoint inhibitor CD274 (programmed cell death ligand-1, PD-L1) and carcinoma marker pan-keratin (cytokeratins)." (PMID 31527554, 2019). "Cancer cells can express ligands for T cell inhibitory receptors such as PDCD1 (PD-1) (ligand is CD274 [PD- L1]), CTLA-4 (ligands are CD80 and CD86), and HAVCR2 (aka TIM3) (ligand reported to be GAL9) to inhibit T cell activation and cytolytic T cell responses." (PMID 28822103, 2018). "Recent successes on cancer immunotherapy targeting the immune checkpoint PD‐1 and/or PD‐L1 (also known as B7‐H1 or CD274) by therapeutic antibodies indicate that activating the immune system is beneficial for treating NSCLC in patients whose lung tumors express PD‐L1." (PMID 28255028, 2017). "The usefulness of blocking CD274 to enhance anti-cancer immunity is under investigation." (PMID 29135455, 2017). "Recently, CD274 (PD-L1) was interested as a promising immunotherapy target in cancer treatment." (PMID 29108360, 2017). "Similar data were obtained for OTX015 and the expression of Cd274 in primary cancer cells." (PMID 28423491, 2017). "Importantly, expression of CD274 was reduced in bulk cancer cells following treatment with miR-106b-5P and miR-93-5P mimics, respectively." (PMID 28423491, 2017). "Increasing evidence indicates that functional monoclonal antibodies of CD274 may potently enhance the antitumor effect in many cancers." (PMID 27855694, 2016). "Interestingly, two of the highly amplified carcinomas and two of the tumors with low-level CD274/PD-L1 amplification were PD-L1 immunonegative (score 0)." (PMID 26918453, 2016). "Over expression of CD274 by tumors, or due to chronic infection allows immune avoidance through T cell anergy, exhaustion, apoptosis and other mechanisms, and high levels of the receptor have been correlated with poor prognoses for certain cancers." (PMID 25889530, 2015). "Besides, CD274 had a relatively strong correlation with KISS1 and was mainly negatively related in pancancer, indicating that CD274 may be a potential checkpoint in cancers that have abnormal KISS1 expression." (PMID 41523580, 2026).
cancer (continued). "The increased CTA repertoire after low-dose 5-aza could be responsible for the observed changes in the IFN-γ signature and CD274 expression in participant 11, which was accompanied by a 20% reduction in the proportion of cancer cells in the TME after 5-aza treatment." (PMID 40091844, 2025). "For example, “don’t eat me” signal expression was either no change or mildly increased in Met1 cells but significantly increased in Met2 cells such as Cd274 (PD-L1), Cd52, and Tbxas1, indicating that these genes may play a significant role in immune evasion of metastatic cancer cells." (PMID 40458726, 2025). "LAMP3+ cDCs were characterized by high immune regulatory gene expression, including CD274 (encoding PD-L1) and PDCD1LG2 (encoding PD-L2), consistent with “mregDCs,” a subset of DCs co-expressing maturation and immunoregulatory genes identified in various cancers." (PMID 38012392, 2024). "Based on the results, we can infer that CD274 may be of significance in various cancers." (PMID 38166842, 2024). "Also, CD274 (PD-L1) showed positive association with SIRPG, whereas RATE1E, CD276 and VEGFA expression seemed to be negatively correlated with SIRPG expression in a subset of TCGA cancers." (PMID 38833156, 2024). "With the availability of TCGA cancer genomics databases, together with RNAseq data, we examined the potential association of COX-prostaglandin signaling with gene signatures that might have an impact on the immune components of TME, such as PD-L1 (CD274)." (PMID 37370700, 2023). "In pathway analysis and cancer immune correlation analysis, we observed that SRSFs were associated with the activation or inhibition of multiple immune pathways, and were also closely related to the expression of multiple immune checkpoints (LAG3, CD274, CTLA4, TIGIT, PDCD1)." (PMID 38015716, 2023). "Specifically, in only 14% (BRCA), 8% (LUAD), and 0% (SKCM) of the patients in the underpredicted group, neither mutations nor miRNA can provide an explanation for the low CD274 expression, which is 0–1% of the total patient population in all three cancer types." (PMID 35289334, 2022). "Overall, both PD-L1 activity scores and CD274 expression levels associate strongly positively with glycolysis and negatively with OXPHOS, consistent with the largely antagonistic trend established for glycolysis and OXPHOS programs in the context of cancer progression." (PMID 36354714, 2022). "Furthermore, the IPRP score was positively correlated with CD274 (PD-L1) in 14 cancers." (PMID 35945345, 2022). "Thus, the relationship between CD274/PDCD1LG2 and the degree of immune cell infiltration was explored, based on TIMER, the data showed that CD274/PDCD1LG2 levels were positively associated with macrophages, dendritic cells, neutrophils, and CD8+ T cells in most cancers." (PMID 36276934, 2022). "Notably, CD274/PD-L1, PDCD1LG2/PD-L2, PDCD1/PD1, cytotoxic T lymphocyte-associated antigen 4 (CTLA4), T cell membrane protein 3 (TIM3; also known as HAVCR2), and lymphocyte activation gene 3 (LAG3) were correlated to FAM72A across different cancers." (PMID 36613817, 2022). "However, the association of these molecules with an epithelial behavior was not as consistently and strongly negative across carcinomas, reminiscent of the previous observations of CD274 expression and PD-L1 signature associating with a partial EMT phenotype." (PMID 36354714, 2022). "Interestingly, GMFG showed a significantly positive association with PD-1 and PD-L2, but not with CD274 (PD-L1) in most cancers." (PMID 33863293, 2021). "CD274/PD-L1 that is induced by NKX2-1 has been a hallmark of cancer immunotherapy along with its receptor PD-1 (also known as PDCD1), which can be targeted by therapeutic antibodies that activate anti-tumorigenic T cells by blocking the interaction between CD274/PD-L1 and PDCD1/PD-131." (PMID 33980985, 2021).
cancer (continued). "Besides, it’s notable that the HS group has a higher expression level of CD274 (p < 0.0001), indicating cancer patients with a high ferroptosis score may be more likely to benefit from PD-L1 inhibitors." (PMID 34938739, 2021). "Furthermore, the correlation of CD274/PDCD1LG2 with cancer immunity was also explored." (PMID 33833994, 2021). "However, a specific gene expression of CD274/PDCD1LG2 in gastrointestinal cancers at a pan-cancer level remains largely unknown." (PMID 33833994, 2021). "This difference could explain the starkly different Kaplan–Meier plots that were identified for the PDCD1/CD274-correlated genes, with the majority of cancers showing the same pattern for the co-expressed genes whilst esophageal and renal were notably different." (PMID 34067485, 2021). "The TIME has come under renewed and intense interest with the success of cancer immunotherapy using immune checkpoint inhibitors that target proteins such as programmed cell death protein 1 (PD-1, a T-cell co-inhibitory receptor) or programmed death ligand 1 (PD-L1, also called B7-H1 or CD274)." (PMID 33590360, 2020). "Among all the findings, down-regulation of CD274 caused by TXT and Ramucirumab in RELF-LC-A1 cells was unexpected results, because cellular stress response signals (i.e eIF2, NFkb, mTOR and OXPHOS) modulated by chemotherapeutic drugs are known to mostly up-regulate PD-L1 expression in cancer cells." (PMID 32993587, 2020). "We examined the relationship between EIF5A2 and immune checkpoints using Spearman analysis and found that EIF5A2 was correlated with CD274, PDCD1LG2, and HAVCR2 in the majority of cancers and PDCD1, CTLA4, LAG3, SIGLEC15, and TIGIT in some tumors." (PMID 40964657, 2025). "Immune checkpoint inhibitors (ICIs) targeting PD-1 (CD279), PD-L1 (CD274), or CTLA-4 (CD152) have revolutionized cancer immunotherapy, leading to significant survival benefits in multiple cancer types." (PMID 41023441, 2025). "Our research shows that PIEZO1 expression is positively correlated with key immune checkpoints, including CD274 (PD-L1), CTLA4, LAG3, PDCD1 (PD-1), PDCD1LG2 (PD-L2), and TIGIT across various cancer types." (PMID 40977743, 2025). "The correlation between SLC2A1 expression and eight immune checkpoints (CTLA4, PDCD1, TIGIT, LAG3, CD274, HAVCR2, PDCD1LG2, and SIGLEC15) was further investigated across multiple cancer types." (PMID 40824962, 2025). "Lastly, while CD274 and TNFSF18 are well-characterized in immune signaling, PSD3’s role in cancer remains poorly defined and should be interpreted with caution." (PMID 40895529, 2025). "Immune checkpoint analysis indicated higher expression of CD274, PDCD1, and other inhibitory molecules, suggesting potential for targeted cancer immunotherapy." (PMID 40963614, 2025). "Cancer cells can exploit immune checkpoints to evade immune responses, and the ADGRG6-high group displayed increased levels of CD274/PDL1 and SIGLEC15 expression." (PMID 40226617, 2025). "TMED2 expression was positively connected with important immune checkpoint markers such as CD274, HAVCR2, PDCD1LG2, and SIGLEC15 in numerous cancer types." (PMID 40519935, 2025). "Hypoxia levels were generally positively correlated with these checkpoint genes, such as CD274 and CTLA4, in various kinds of cancers." (PMID 41419193, 2025). "The results showed that CD274 and FCGR2A proteins have been identified as possible cancer therapeutic targets, indicating the potential and importance of these proteins in anti-cancer drug development." (PMID 39857814, 2025). "HPV-positive CC tumors exhibited epithelial cells with significant enrichment of immune checkpoint ligands (LGALS9, CD274, and TNFRSF14), whereas HPV-negative carcinomas predominantly activated the CD80/86-CTLA4 pathway." (PMID 41035636, 2025).
cancer (continued). "Not only that, our results also reveal a positive correlation between LAPTM4A and multiple immune checkpoint (ICP) gene expressions, including the well-known CD274, PDCD1, and CD80, which tend to suppress effector T cells to promote cancer development." (PMID 38613802, 2024). "Then, immune checkpoints analysis shown that UBE2C had a negative correlation with immune checkpoints, such as CD274(PD-1), PDCD1(PD-L1), CTLA4, TIGIT, LAG3, HAVCR2, and PDCD1LG2 in a great many cancers." (PMID 38370368, 2024). "We also used ImmuCellAI to explore the correlation between YY1, CD274, and LAG-3 expression and immune infiltration in various cancers." (PMID 39796650, 2024). "Our analysis indicated a positive correlation between B3GNT5 and immune activation markers, including CD276, PVR, NT5E, STING1, and TNF-SF18, as well as immunosuppressive genes TGF-ΒR1, IL-10PR, KDR, CD274, PDCD1LG2, IL-10, and IDO1 in the pan-cancer cohort." (PMID 39671359, 2024). "PD-L1, also known as B7-H1 or CD274, contributes to the inhibition of the cancer-immunity cycle by binding to negative regulators of T-cell activation such as PD-1 and B7.1 (CD80)." (PMID 38638433, 2024). "Recent studies have shown that neutrophils expressing programmed death-ligand 1 (PD-L1, also known as CD274) are immunosuppressors in cancers." (PMID 38787253, 2024). "PD-1 functions as PD-L1’s T-cell-inhibitory receptor, and both PD-L1 (CD274) and PD-L2 (CD273; also known as B7-DC) are expressed in cancer cells and APCs in the TME." (PMID 39273605, 2024). "We first used RT-qPCR to analyze the levels in PB cells of mRNAs encoding the immune checkpoint genes (ICGs) PDCD/CD274 in view of the cancer resistance of Klf1(K74R) mice as well as increased levels of PDCD and CD274 in aged or tumorigenic mice." (PMID 38752723, 2024). "Programmed cell death 1 ligand-1 (PD-L1, also known as CD274 and B7-H1), identified by Lieping Chen in 1999, represents one of the most important co-inhibitory molecules for cancer immunotherapy." (PMID 38257366, 2024). "We found CD47 had strong correlation with CD274, LAG3, IDO1 and TNF receptor superfamily in pan-cancer(r > 0.2, p < 0.05)." (PMID 38720108, 2024). "These consistent outcomes across various cancer types highlighted the correlation between TUBA1C and CD274, positioning TUBA1C as a potential biomarker for targeted therapy." (PMID 39301023, 2024). "In particular, Hypo-MS4 activity was positively associated with the expression levels of immune checkpoint genes, namely, CD274, PDCD1LG2, and IDO1, in multiple cancer types (P ≤ 0.01)." (PMID 38566132, 2024). "Subsequently, we also explored the correlation between the expression levels of LRP6 and the expression levels of common immune checkpoints in 33 cancers, such as SIGLEC15, IDO1, CD274, HAVCR2, PDCD1, CTLA4, LAG3 and PDCD1LG2." (PMID 38226972, 2024). "Meanwhile, several immune check point genes, such as CD274 (PD-L1), are highly expressed in NRF2-activated cancer cells." (PMID 38241355, 2024). "Our comprehensive analysis revealed that PLEK2 expression was significantly associated with various immune regulatory genes across multiple cancer types, including CD276 (B7-H3), CD274 (PD-L1), and FAS." (PMID 39546161, 2024). "Our analysis revealed that elevated PLEK2 expression was significantly associated with increased expression of several key immune checkpoint molecules, such as CD276 (B7-H3), CD274 (PD-L1), LGALS9, PVR (CD155), and FAS across a wide spectrum of cancers." (PMID 39546161, 2024). "The exhaustion of CD8 + T and NK cells, along with the overexpression of molecular markers such as LAG3, CTLA4, CD274, PD-L1, and HAVCR2, have been identified as key mechanisms by which cancer cells can escape host immunity." (PMID 38956740, 2024). "In the radar plots analyzing correlations between gene expression and TMB and MSI, CCR8, CD274, and PDCD1 expression levels showed significant positive correlations with TMB and MSI in several cancer types." (PMID 39273290, 2024).
cancer (continued). "We identified a significant positive correlation between TUBA1C and CD274 at both the pan-cancer and pan-tissue levels, suggesting that TUBA1C has a strong and universal connection with CD274 under both physiological and pathological conditions." (PMID 39301023, 2024). "And Kyoto Encyclopedia of Genes and Genomes (KEGG) analysis revealed that the upregulated genes of Macro_Cd274 enriched in the pathway “PD‐L1 expression and PD1 checkpoint pathway in cancer”." (PMID 38962427, 2024). "When investigating the relationship between immune checkpoint expression and PSME3, we observed that among the 33 cancers, CD276 and CD274 exhibited the highest positive correlation with PSME3, followed by VEGFA, HMGB1, THR4, BTNA2, and ENTDD1." (PMID 38312840, 2024). "K-M survival analysis indicated that OS and PFS were better in cancer patients treated with PDCD1, CD274, and CTLA4 with elevated KLRB1 expression." (PMID 37988189, 2023). "mAbs targeting CTLA4, PDCD1, CD274, and LAG3 have been approved by the FDA for second- and first-line treatment against cancer, whereas mAbs targeting ICOS and CD40 are under investigation." (PMID 37215135, 2023). "Studies in the past decades provided ample data that cancer plasticity can be manifested also in the expression of a vast array of immune cell genes; best-known examples are PDL1/CD274, CD47, or IDO, and we termed it immunogenic mimicry (IGM)." (PMID 36754910, 2023). "For instance, ICOS has positive relationships with PDCD1, TIGIT, CD274, and CTLA4 in the majority of cancer types, indicating a broad co-expression landscape." (PMID 36855091, 2023). "We found that PTPN6 expression was positively correlated with PDCD1, CD274, CTLA4, LAG3, HAVCR2, and CD244 in most cancer types in TCGA, including LGG and GBM." (PMID 37737713, 2023). "A highly positive correlation between CD274 (PD-L1-encoding gene) and pdcd1lg2 expression in almost all cancers was observed in our results, which might suggest that targeting PD-L1 will not show apparent benefits since PD-L2 is still functional and plays a redundant role." (PMID 37006239, 2023). "It has two distinct ligands, PD-L1 (CD274, B7H1) and PD-L2, that are expressed on APC and in several cancer subtypes, and in chronic viral-infected cells." (PMID 37345088, 2023). "On the other hand, a meta-analysis of CD274 expression in PMDs confirmed an increase in CD274 in the transition from normal to PMD and cancer." (PMID 37190121, 2023). "The most promising immune checkpoint therapeutic targets, CD274 (PD‐L1) and PDCD1LG2 (PD‐L2), were expressed at low levels in each cancer cell population." (PMID 36529697, 2023). "The novel immunotherapy agents such as inhibitors of PDCD1, TIGHT, IDO1, CD274, CTLA4 and LAG3 were considered had potential survival benefit in several cancers." (PMID 37608927, 2023). "Programmed death-ligand 1 (PD-L1, also known as CD274 or B7-H1) is a ligand of immunosuppressive checkpoint programmed death 1 (PD-1) and is overexpressed in various cancers." (PMID 36719382, 2023). "Its binding to LAG3 results in T cell depletion, mechanisms of immune evasion of the cancer and resistance to anti-PDCD1/CD274 therapy." (PMID 37215135, 2023). "Programmed death ligand 1 (PD-L1, also known as B7-H1 and CD274) is an immune checkpoint protein that is often overexpressed in a variety of human cancers." (PMID 36928177, 2023). "Almost all cancers showed a significant relationship between MRPL13 and immune checkpoint suppressor genes, such as VEGFA, CD274 (PD-L1), and CTLA4." (PMID 37827692, 2023). "For example, the MHC class and CD274 work in cancer and immune cells, and CCL5, CXCL10 and IFNB1 are downstream of ISRE and induce immune cell infiltration into cancer tissue." (PMID 37543704, 2023).